ALPP (alkaline phosphatase, placental)
Description:
Alkaline phosphatase that can hydrolyze various phosphate compounds.
Synonyms: PLAP-1; PLAP; PALP; ALP
Tractability: Small molecule: a structure with a bound ligand is known. Antibody: its Gene Ontology location is reachable by antibodies, with high confidence; UniProt places it where antibodies can reach, with medium confidence; UniProt predicts a signal peptide or a membrane-spanning region; the Human Protein Atlas places it where antibodies can reach. PROTAC: ubiquitination databases record sites on it; a small molecule that binds it is known.
Target class: Enzyme; Phosphatase
Chemical probes: ML085, ML095
Gene: Protein-coding gene on chromosome 2 (232,378,724 to 232,382,889, forward strand). Ensembl gene ENSG00000163283.
Subcellular location: Cell membrane
Subcellular location (Human Protein Atlas): Plasma membrane
Pathways (Reactome):
Vesicle-mediated transport: Intra-Golgi traffic
Gene Ontology:
Molecular function: alkaline phosphatase activity; protein binding; magnesium ion binding; zinc ion binding; phosphatase activity
Cellular component: cell surface; plasma membrane
Genetic constraint (gnomAD): Loss-of-function variants: 39 observed, 45.61 expected, observed/expected ratio (o/e) 0.86, 90% interval 0.66 to 1.12. The upper end of that interval is the gene's LOEUF score, 1.12, which puts it in group 4 of 6, group 1 being the genes least tolerant of losing a copy. Missense variants: 550 observed, 650.14 expected, observed/expected ratio (o/e) 0.85, 90% interval 0.79 to 0.91. Synonymous variants: 226 observed, 263.76 expected, observed/expected ratio (o/e) 0.86, 90% interval 0.77 to 0.96.
Homologues: Orthologues: chimpanzee ALPP (98% identical), macaque ALPP (92% identical), dog ALPI (76% identical), mouse Alpi (74% identical), mouse Akp3 (73% identical), mouse Alppl2 (73% identical), rat Alpg (73% identical), rat Alpi (73% identical), rat Alpp (73% identical), rat Akp3 (71% identical), tropical clawed frog alpi (59% identical), zebrafish alpi.2 (55% identical), and 13 more. Paralogues in human: ALPG (96% identical), ALPI (86% identical), ALPL (52% identical).
Diseases named in the same sentence as ALPP in open-access papers:
ALPP is named in the same sentence as 55 diseases in open-access papers, as found by Europe PMC text mining. Sharing a sentence is not in itself a finding about the gene and the disease. The quoted sentences say what the papers report.
germ cell tumor (16 papers, 2009 to 2026). A benign or malignant, gonadal or extragonadal neoplasm that originates from germ cells. "ALPP encodes placental alkaline phosphatase, which has been reported as a tumor marker of reproductive system, including ovarian cancer, seminoma, and testicular germ cell tumors." (PMID 32547950, 2020). "While ALPP overexpression has been observed in various germ cell tumors and specific cancers, its functional relevance and regulatory mechanisms in CCA remain poorly understood." (PMID 41209549, 2025). "ALPP has also been reported to be overexpressed in multiple solid tumor types, including ovarian and testicular germ cell tumors, and endometrial carcinoma." (PMID 40897818, 2025). "Notably, ALPP, in addition to its high expression in the placenta during pregnancy, has been found to be aberrantly upregulated in various germ cell tumors and specific types of cancer." (PMID 41209549, 2025). "Moreover, ALPP has also been identified as a biomarker of various germ cell tumors such as seminoma and dysgerminoma." (PMID 39981229, 2025). "In addition, ALPP has been identified as a reliable biomarker of diverse germ cell tumors." (PMID 39981229, 2025).
endometrial cancer (5 papers, 1994 to 2025). Primary or metastatic malignant neoplasm involving the endometrium (mucous membrane that lines the endometrial cavity). "The study population is patients with ALPP-positive metastatic ovarian and endometrial cancer." (PMID 37185744, 2023). "The First-in-Human Anti-ALPP CAR-T Cells Immunotherapy for Ovarian and Endometrial Cancer (NCT04627740) clinical trial is a single-arm, single-center, open-label study of anti-alkaline phosphatase placental (ALPP)-positive CAR-T cells." (PMID 37185744, 2023).
breast carcinoma (3 papers, 2020 to 2021). "ALPP encodes an alkaline phosphatase, and its increased expression has been observed in several cancers, including breast cancer and intratubular germ cell neoplasia." (PMID 34518802, 2021). "In future studies, whether exosomal ALPP is necessary for resistance-induced breast cancer metastasis needs to be further explored." (PMID 33879771, 2021). "Meanwhile ALPP, JUND, ZBTB7A in gastric cancer, prostate cancer, breast cancer 33-35 and other cancers promote the progress of cancer." (PMID 32626531, 2020).
preeclampsia (3 papers, 2014 to 2025). Preeclampsia is a hypertensive disorder of pregnancy that is characterized by new-onset hypertension with proteinuria presenting after 20 weeks of gestation, and depending on mild or severe forms may initially present with severe headache, visual disturbances, and hyperreflexia. "The observed reduction in ALPP mRNA despite previous reports of increased protein levels in preeclamptic placentas underscores a well-documented transcript-protein disconnect in preeclampsia, potentially reflecting adaptive mechanisms such as enhanced protein stability or translational efficiency." (PMID 41444673, 2025).
hepatocellular carcinoma (2 papers, 2025). A malignant tumor that arises from hepatocytes. "Recent studies have shown that ALPP is overexpressed in hepatocellular carcinoma and is associated with enhanced cellular motility, suggesting a potential pro-tumorigenic role." (PMID 41209549, 2025). "Interestingly, our preliminary findings showed elevated ALPP expression by human hepatocellular carcinomas, suggesting a possible pregnancy-independent tumorigenic role (unpublished results)." (PMID 39981229, 2025). "Additionally, our recent study identified unusually elevated ALPP expression in human hepatocellular carcinomas with enhanced motility, suggesting a pro-tumorigenic role that extends beyond its placenta-specific functions (unpublished results)." (PMID 39981229, 2025). "Placental alkaline phosphatase (ALPP) is one of tissue-specific ALP isozymes expressed mostly during pregnancy, however it was found to be differentially upregulated in certain hepatocellular carcinomas by us recently." (PMID 39981229, 2025).
ovarian carcinoma (2 papers, 2020 to 2023). A malignant neoplasm originating from the surface ovarian epithelium. "Thus, FXYD3 and ALPP could be used as biomarkers for primary sites of ovarian tumors and TSPAN15 as a biomarker for ovarian cancer metastasis." (PMID 37047289, 2023).
Sepsis (2 papers, 2022 to 2025). Sepsis is defined as life-threatening organ dysfunction caused by a dysregulated host response to infection. "Our results indicate that ALPP transgenic mice are more susceptible to LPS-induced sepsis and are more resistant to male-to-female skin graft rejection." (PMID 39981229, 2025). "Our results showed that ALPP transgenic mice are in fact more susceptible to LPS-induced sepsis and lethality in comparison to the WT B6 mice." (PMID 39981229, 2025). "In this study, we generated ALPP transgenic mice and tested these mice in the LPS-induced sepsis and male-to-female skin graft rejection models." (PMID 39981229, 2025). "To investigate the immune modulatory effect of ALPP on LPS-induced sepsis and the phagocytic activity of monocytic cells, we carried out a cytokine multiplex assay to measure serum levels of specific pro-inflammatory and anti-inflammatory cytokines in LPS-treated mice." (PMID 39981229, 2025). "Interestingly, comparable analyses of the younger mice receiving the same LPS doses showed that ALPP transgenic mice were more vulnerable than the WT B6 mice to LPS-induced sepsis." (PMID 39981229, 2025).
ZIKV infection (2 papers, 2020 to 2024). "The specific expression of ALPP in the placenta might explain the unique vulnerability of this tissue to ZIKV infection and the associated adverse pregnancy outcomes." (PMID 39254430, 2024). "Furthermore, ectopic expression of ALPP in ALPP−/− JEG-3 cells rescued the susceptibility of these cells to ZIKV infection." (PMID 32934082, 2020). "BIP associates with ALPP and is essential for ZIKV infection." (PMID 32934082, 2020). "To assess whether the GPI anchor or the hydrophobic stretch at the C terminus is required for the function of ALPP in ZIKV infection, we constructed an ALPP-C-terminus-deleted protein (ALPP-ΔC33) and an ALPP-D484W mutant that rendered a loss of the GPI linker." (PMID 32934082, 2020). "Taken together, these results suggest that ALPP plays an important role in ZIKV infection through its direct interaction with ZIKV proteins." (PMID 32934082, 2020). "Together, our results provide evidence suggesting that ALPP exclusively facilitates ZIKV infection in placental trophoblasts and fetal brain cells, based on data obtained with JEG-3 and U-251 MG cells." (PMID 32934082, 2020). "The chaperone activity of BIP promoted ZIKV infection and mediated the interaction between ALPP and ZIKV proteins." (PMID 32934082, 2020). "Here, we found that ALPP, an alkaline phosphatase expressed primarily in placental tissue, promoted ZIKV infection in both human placental trophoblasts and astrocytoma cells." (PMID 32934082, 2020). "Deletion of 33 amino acids at the C terminus significantly inhibited the function of ALPP in ZIKV infection." (PMID 32934082, 2020). "We designed CRISPR/Cas9 sgRNAs that target each of the enriched hits from our primary screen and confirmed that ALPP is a key host factor for ZIKV infection in U-251 MG cells." (PMID 32934082, 2020). "Here, we identified an alkaline phosphatase (ALPP) that is expressed primarily in placental tissue and promotes ZIKV infection by colocalizing with ZIKV proteins and preventing their proteasome-mediated degradation." (PMID 32934082, 2020). "Depletion of ALPP in JEG-3 cells significantly attenuated ZIKV infection at different infection doses, significantly enhanced cell viability after ZIKV infection, and reduced ZIKV-induced cytopathic effects (CPEs)." (PMID 32934082, 2020). "ALPP stabilises the ZIKV replication complex and is primarily expressed in the placenta, potentially contributing to the severe congenital abnormalities associated with ZIKV infection during pregnancy." (PMID 39254430, 2024). "Our data raise the possibility that ALPP or BIP can be targeted to intervene in ZIKV infection." (PMID 32934082, 2020). "The phosphatase activity of ALPP could be required for optimal ZIKV infection, and ALPP is stabilized by BIP via its chaperone activity." (PMID 32934082, 2020). "To test whether BIP chaperone activity is required for its regulation of ALPP and ZIKV infection, we reconstituted BIP-depleted cells with CRISPR-resistant wild-type BIP or ATPase-defective mutants." (PMID 32934082, 2020). "To gain more insight into the functional mechanism of ALPP, we assessed whether the catalytic activity of ALPP is required for promoting ZIKV infection." (PMID 32934082, 2020). "Interestingly, we observed a substantial reduction in ZIKV infection in ALPP-KO U-251 cells and ALPP-KO JEG-3 cells." (PMID 32934082, 2020). "Similarly, overexpression of ALPP in HEK 293T cells, a cell line with minimal expression of ALPP, significantly enhanced the susceptibility of these cells to ZIKV infection." (PMID 32934082, 2020). "BIP chaperone activity is essential for ZIKV infection and ALPP stability." (PMID 32934082, 2020). "ALPP promotes ZIKV infection in human placental trophoblast cells and astrocytes." (PMID 32934082, 2020). "ALPP might be targeted to block ZIKV infection in the placenta and to ameliorate microcephaly." (PMID 32934082, 2020). "This indicates that ALPP may play a role in ZIKV infection in the placenta." (PMID 32934082, 2020).
ZIKV infection (continued). "Thus, the catalytic activity of ALPP is important for its role in promoting ZIKV infection." (PMID 32934082, 2020). "In addition, the function of ALPP in ZIKV infection depends on its phosphatase activity." (PMID 32934082, 2020). "Together, these results demonstrate that ALPP may play an essential role in ZIKV infection." (PMID 32934082, 2020). "We further demonstrated that the phosphatase activity of ALPP may be required for ZIKV infection." (PMID 32934082, 2020). "To confirm the interaction between BIP and ALPP, we immunoprecipitated ectopically expressed Flag-tagged ALPP and found that BIP was indeed pulled down both in the absence (left) and in the presence (right) of ZIKV infection." (PMID 32934082, 2020). "In contrast, the GPI-defective mutant (D484W) did not affect the function of ALPP in ZIKV infection, which indicated that the addition of a GPI anchor (mature form) is not required for ALPP function in ZIKV infection." (PMID 32934082, 2020). "We found that the derived cell line (ALPP−/−, clone 8) was resistant to ZIKV infection but not to influenza A virus (IAV) or dengue virus (DENV) infection." (PMID 32934082, 2020). "In this study, we demonstrated that BIP cooperates with ALPP and plays roles exclusively in ZIKV infection and not in DENV infection." (PMID 32934082, 2020). "We established a U-251 MG cell line stably expressing Flag-tagged ALPP, isolated a cell clone (clone 15) with a high level of ALPP expression by fluorescence-activated cell sorter (FACS) analysis, and then performed coimmunoprecipitation experiments in the context of ZIKV infection." (PMID 32934082, 2020). "In addition, ALPP knockout in HK2 cells, an immortalized proximal tubule epithelial cell line, also reduced ZIKV infection." (PMID 32934082, 2020). "Finally, the enzymatic activity of ALPP could also facilitate its proper structural conformation and interaction with BIP, which stabilizes ALPP during ZIKV infection." (PMID 32934082, 2020). "The mutants could not rescue the ALPP levels or ZIKV infection, which suggested that BIP chaperone activity is required for ZIKV infection." (PMID 32934082, 2020). "Additionally, ALPP might also enhance ZIKV replication in other tissues, as exemplified by our findings with the U-251 MG and HK2 cell lines, which were previously confirmed to be highly permissive to ZIKV infection." (PMID 32934082, 2020). "In fact, in the absence of ALPP, BIP itself cannot ensure the stability of ZIKV proteins and fails to support ZIKV infection." (PMID 32934082, 2020).
cholangiocarcinoma (1 paper, 2025). A carcinoma that arises from the intrahepatic biliary tree (intrahepatic cholangiocarcinoma) or from the junction, or adjacent to the junction, of the right and left hepatic ducts (hilar cholangiocarcinoma). "Interestingly, although tumor-infiltrating B lymphocytes are often linked to better outcomes in cholangiocarcinoma and related biliary cancers 34, the co-occurrence of high ALPP expression with increased B cell/DC infiltration in our study suggests a complex immune context." (PMID 41209549, 2025). "Future studies should validate the prognostic significance of ALPP in larger, independent CCA cohorts and investigate the mechanistic underpinnings of ALPP in cholangiocarcinoma." (PMID 41209549, 2025). "Our results are consistent with the known importance of PI3K-Akt signaling in cholangiocarcinoma progression 41; thus, it is plausible that ALPP contributes to tumor growth through this pathway." (PMID 41209549, 2025). "Our findings suggest that ALPP-high cholangiocarcinoma tumors could be fostering an immunosuppressive microenvironment." (PMID 41209549, 2025).
colorectal cancer (1 paper, 2019). A primary or metastatic malignant neoplasm that affects the colon or rectum. "The expression level of ALPP in colorectal cancer and adjacent normal tissues was almost undetectable, which was supported by data in TCGA." (PMID 30569605, 2019).
gallstones (1 paper, 2020). Solid crystalline precipitates in the biliary tract, usually formed in the gallbladder, resulting in the condition of cholelithiasis. "ALPP and GPR87 exhibited to have a potential for predicting risk of GBC for patients with gallstones." (PMID 32547950, 2020). "ALPP and GPR87 are potential biomarkers for predicting cancer risk in patients with gallstones." (PMID 32547950, 2020).
Lewy body dementia (1 paper, 2018). A progressive form of dementia characterized by the presence of protein deposits called Lewy bodies in the midbrain and cerebral cortex, and loss of cholinergic and dopaminergic neurons. "After extensive meta-analysis, we only found alterations at mRNA level for AZGBP1 and ALPP in Parkinson’s disease, and LGALS3BP in Lewy body dementia; and thus, suggesting that the deregulated proteins identified in our study were mostly specific of AD." (PMID 29541381, 2018).
metastatic tumor (1 paper, 2023). "The three potential targets FXYD3, ALPP, and TSPAN15 were further explored regarding their expression profile in non-tumoral (normal), primary site tumor, and metastatic tumor tissues, using GeneChip data from TNMplot database." (PMID 37047289, 2023).
pancreatic carcinoma (1 paper, 2023). "The potential target for AptaC4 in Caov-3, ALPP, is a surface protein in epithelial cells, and is overexpressed in pancreatic carcinoma." (PMID 37047289, 2023).
serous ovarian carcinoma (1 paper, 2022). "The expression pattern in tumour tissue of the glycosylphosphatidylinositol (GPI)-anchored placental alkaline phosphatase (ALPP) is suggested as a complementary biomarker to MUCIN-16 and WFDC2 for early detection in serous ovarian carcinoma." (PMID 35406529, 2022).
Stillbirth (1 paper, 2024). Death of the fetus in utero after at least 22 weeks of gestation. "An illustrative example of downregulated genes in unexplained stillbirths is ALPP, which is a reported STB marker in term pregnancies." (PMID 38791219, 2024).